TLR3 (toll like receptor 3)
Diseases named in the same sentence as TLR3 in open-access papers (continued):
Sharing a sentence is not in itself a finding about the gene and the disease.
tumor (continued). "What does viral TLR-3 activation mean for the tumor microenvironment?" (PMID 37974615, 2023). "Furthermore, anthracyclines stimulate the production of type I interferons (IFNs) by tumor cells through activation of the endosomal pattern recognition receptor (PRR) Toll-like receptor 3 (TLR3), contributing to the efficacy of chemotherapy." (PMID 37781042, 2023). "In addition, conjugates can be designed to induce apoptosis in tumor cells upon antibody-mediated uptake of TLR3 agonists." (PMID 36913398, 2023). "Here, we develop a surgically optimized biodegradable hyaluronic acid-based hydrogel for sustained intraoperative delivery of Toll-like receptor 3 agonist poly(I:C) and demonstrate that it significantly reduces tumor recurrence after surgery in multiple mouse models." (PMID 37467718, 2023). "In addition, for several biofluids from patient or mouse tumor grafts, there was a substantial reduction in the reporter response in the presence of a TLR3-blocking antibody." (PMID 37894949, 2023). "Finally, there is one important question to determine: what are the consequences of the release of TLR3 agonists by necrotic cells for tumor growth?" (PMID 37894949, 2023). "Either directly or indirectly, TLR3 triggers both innate and adaptive immune responses;, it suppresses tumor cell proliferation and promotes tumor cell apoptosis; it regulates tumor angiogenesis; it has also been found to enhance chemosensitivity and radiosensitivity." (PMID 36479129, 2022). "This has been previously demonstrated in vivo with a DC-based vaccine containing a miR148a inhibitor, poly I:C (TLR3 agonist), and tumor antigen, which promoted enhanced anti-tumor immunity and survival by expanding mature DCs and suppressing Treg and MDSC development." (PMID 36248881, 2022). "Similarly, administration of a TLR3 agonist, ARNAX, with a tumor-associated antigen (TAA) enhanced anti-tumor immunity and sensitized ICB-resistant tumors to anti–PD-L1 therapy." (PMID 36248881, 2022). "Although we acknowledge that the exact role of TLR-3 signaling in PDAC is unknown, TLR-3 agonists were found to enhance tumor cell lysis by human γδ T cells in human pancreatic cells." (PMID 35326528, 2022). "In recent years, TLR3 overexpression is also found in multiple cancer types, but increasing evidence reveals that in tumorigenesis and progression, the dual or contradictory roles of TLR3 correlate with heterogeneous tumor cells and complex microenvironment." (PMID 35165523, 2022). "In addition to the immunomodulatory effects, TLR-3 stimulation is theorized to restrain tumor cell proliferation and induce apoptosis in tumor cells." (PMID 35326528, 2022). "This could mean that individual different responses to rintatolimod in this study could be present, depending on the level of TLR-3 expression in the tumor cells." (PMID 35326528, 2022). "Some chemotherapeutics, such as anthracyclines, promote the activation of TLR3 in mouse and human tumor cells, leading to the secretion of type I IFNs, which then activate an autocrine or paracrine IFNAR­dependent circuit that drives the expression of some ISGs." (PMID 35292881, 2022). "Thus, further research is needed to elucidate the role of TLR3 in tumor and immune cells and its dominant role in TME." (PMID 36389785, 2022). "TLR3 stimulation (e.g., by interferon type I signaling) results in cancer cell apoptosis in human and mouse models, or in the suppression of cancer cell migration, depending on the tumor stage." (PMID 36411434, 2022). "However, a recent study found the anti-tumor efficacy of neoantigen/toll-like receptor 3 (TLR3)/CD40 agonist vaccine and neoantigen-specific CX3CR1+ CD8+ T cell generation relied on CD40 and CD80/86, rather than the CD70 signaling pathway." (PMID 36263174, 2022). "CD103+ cDC1 and CD11b+ cDC2 are the only TLR3-expressing groups at tumor sites." (PMID 36365103, 2022).
tumor (continued). "Thus, targeted delivery of ICD inducers and TLR3 agonists into tumor cells would be an ideal way to activate tumor-infiltrating DCs in situ and avoid interactions in the immune milieu of other sites." (PMID 35148751, 2022). "A previous study found that primary tumor-derived exosomes could activate lung epithelial cell Toll-like receptor 3 (TLR3) to initiate neutrophil recruitment and pulmonary PMN formation." (PMID 36158661, 2022). "Moreover, TLR3-TICAM1 pathway promotes the development of important immune cells to resist tumor, such as dendritic cells and macrophages." (PMID 35933370, 2022). "Furthermore, treating tumor-bearing mice with the TLR3 and MDA-5 ligand poly I:C reduced the suppressive activity of MDSCs and induced the production of high amounts of type I IFNs." (PMID 35292881, 2022). "Similarly, synthetic vaccine nanoparticles using poly (γ-glutamic acid) tumor antigens and TLR-3 agonists have been demonstrated." (PMID 36358857, 2022). "Indeed, IL-12 released by TLR3-activated DCs renders NK cells responsive through TLR3 to dsRNA, increasing their anti-tumor/anti-viral cytotoxicity." (PMID 36672572, 2022). "Moreover, GSEA of TLR3 in KIRC, LGG and PAAD showed that TLR3 was closely related to tumor immune microenvironment." (PMID 36419829, 2022). "The addition of OX40/TLR3/9 immunotherapy to SBRT resulted in local depletion of Tregs and tumor macrophages and reduced Treg-associated gene expression (FoxP3), suppressed macrophage-associated gene expression (IL-8), and suppressed exhausted T cell-associated gene expression (CTLA4)." (PMID 35055015, 2022). "TLR3 actively regulates multiple aspects of tumor development." (PMID 36479129, 2022). "Intriguingly, increasing evidence has demonstrated that TLR3 is also expressed in tumor cells." (PMID 33986756, 2021). "Given that cDC2 is involved in CD4+ T cell differentiation and activation, CD300a on cDC2, rather than cDC1, may regulate Treg cells activation by inhibiting the TLR3–IFN-β pathway in tumor microenvironment." (PMID 34751648, 2021). "Among all, signaling via TLR3, 7, 8, and 9 had been shown as a crucial route in tumor biology." (PMID 34124272, 2021). "Lipopolysaccharide-primed MSC1 showed a suppressive effect on proliferation, migration, and invasion of tumor cells and attenuated tumor growth and metastasis in mouse tumor models, whereas MSC2, primed with TLR3 agonist poly(I:C), had the opposite, tumor-supporting effects in these model systems." (PMID 34834485, 2021). "Further mechanistic investigations on the dual roles of TLR3 in tumor biology are needed." (PMID 33986756, 2021). "Additionally, tumor EV-derived RNAs were foundto activate the Toll-like receptor 3 (TLR3) in lung epithelial cells, leading tothe stimulation of chemokine secretion and increased neutrophil infiltration tofavor lung metastasis." (PMID 34336602, 2021). "The activation of TLR3 in both tumor cells and the tumor microenvironment, such as in typical innate immune cells, might play an opposing role in tumor progression." (PMID 33986756, 2021). "Despite recent failure of TLR agonists in the clinic and recent work suggesting a possible contribution of TLR3 to tumor progression, TLR-based therapies combined with different types of DNA-damaging agents are currently in clinical trials for treatment of many cancer types." (PMID 34769259, 2021). "Thus, TLR3 treatment leads to a unique intra-tumor T cell phenotype characterized by distinct CD8 RNA expression profile and the loss of a regulatory T cell gene signature 24 hours post-treatment." (PMID 34381732, 2021). "On the other hand, the balance of TLR3 and CD300a expressions in DCs may also be important for Treg activation and tumor development." (PMID 34751648, 2021). "However, TLR3 expression both in tumor cells and intratumoral cells correlates with prolonged survival." (PMID 33986756, 2021). "In this way, poly(I:C) nanoparticles promoted the tumor properties of TLR3 signals." (PMID 33469538, 2020).
tumor (continued). "In our model, antitumor responses associated to tumor regression were absent in mice implanted with Tlr-3-/- tumors, thus suggesting a role of this ling pathway in the synergism between CTX and anti-PDL Abs." (PMID 32290265, 2020). "TLR3 was significantly higher expressed in tumor tissues than adjacent tissues (p = 2.248E-7)." (PMID 33036630, 2020). "Further work is required to evaluate whether CD103+ cDC1s utilize similar or distinct STAT3 anti-inflammatory or anti-tumor mechanisms in response to TLR3 agonist stimulation." (PMID 31947933, 2020). "Riboxxol is a synthetic TLR3 agonist that triggers Ripk1 activation and that is well tolerated when administered systemically or via intra‐tumour injections." (PMID 32419365, 2020). "We also examined whether RT needs to be delivered to the same tumor receiving injections of Flt3L and TLR3/CD40 agonists." (PMID 33110069, 2020). "IHC performed on FFPE NSCLC specimens showed TLR3 and caspase-3 expression in tumor cells." (PMID 32093313, 2020). "We can speculate that the antitumor effect of TLR3 activation on tumor cells depends on the histological characteristics of the NSCLCs and the environmental immune context in which these tumors develop." (PMID 32093313, 2020). "Meanwhile, low TLR3 expression was inversely correlated with tumor size and venous infiltration." (PMID 33173017, 2020). "TLR3 was significantly higher expressed in tumor than adjacent normal tissues." (PMID 33036630, 2020). "The detection of tumor-derived exosomal RNAs by TLR3 in lung epithelial cells might also be involved in tumorigenesis." (PMID 33633744, 2020). "Interestingly, tumor exosomal RNAs activate alveolar epithelial toll-like receptor 3 (TLR3) to induce chemokines (CXCL1, CXCL2, CXCL5, and CXCL12) that are critical for neutrophil recruitment and lung pre-metastatic niche formation." (PMID 33101283, 2020). "The presence of exogenous or endogenous ligands, inhaled or released from dying tumor cells, might sustain TLR3 activation, thus explaining the improved prognosis of NSCLC patients with high TLR3 expression in tumor cells." (PMID 32093313, 2020). "We explore the possibility that TLR3-mediated apoptosis activates immune cells against the tumor." (PMID 32093313, 2020). "In addition, in vivo anti-tumor effects of TLR3 ligand, Poly(I:C) are possibly mainly due to an induction of cell death upon direct stimulation of TLR3 by TLR3 ligand, Poly(I:C) and also the recruitment of tumor-specific CD8+ T lymphocytes." (PMID 33036630, 2020). "Based on our findings, we speculate favorable prognostic value of TLR3 mRNA depends on the abundance of mRNA of tumor versus tumor-infiltrating immune cells origin in a whole-transcriptome analysis." (PMID 31582772, 2019). "In our model, poly(I:C)c was used as MDA5-specific agonist and we cannot rule out potential TLR3 engagement; nevertheless, we did not observe cross-presentation of tumor-associated antigen by MDSC." (PMID 31694706, 2019). "Notably, combining CD40 agonists with TLR3 activation was shown to be sufficient to reverse the immunosuppressive phenotype of tumor-infiltrating DC into APCs capable of priming anti-tumor T cell responses." (PMID 31031762, 2019). "Besides on tumor cells, TLR3 protein resulted to be expressed on immune cells in nearly half of the analyzed NSCLC cases, considering immune cells that infiltrated the stroma or tumor cell islets." (PMID 31582772, 2019). "Here, we show that CD103+ cDC1 and, to a much lesser extent CD11b+ cDC2, are the only populations expressing TLR3 at the tumor site, and consequently could be potential targets of poly A:U." (PMID 30949170, 2019). "However, few studies have evaluated the functions and the prognostic significance of TLR3 expression separately in tumor and immune cells." (PMID 31582772, 2019).
tumor (continued). "It has been also shown on human cancer cell lines, stimulation of tumor expressed TLR3 results in metabolic reprogramming manifested by aerobic glycolysis, enhanced cell migration, elevation of reactive oxygen species as well as upregulation of various genes involved in cancer progression." (PMID 30976817, 2019). "TLR3 has a role in mediating the anti-tumor activities of NK cells." (PMID 30728068, 2019). "Other groups, in both mouse models and patients, have utilized radiation to release tumor antigens combined with a TLR3 agonist and Flt3L to expose DCs to antigen and foster DC maturation, resulting in immune-mediated tumor elimination at distant sites (known as the abscopal effect)." (PMID 31921140, 2019). "Treatment of HT1376 xenografts in immune-deficient hosts with targeted delivery of TLR3 agonist did not induce adverse effects and only modestly inhibited tumor growth when compared to controls." (PMID 30824859, 2019). "Thus, TLR3 activation by dsRNA that is released by CS-damaged cells can increase inflammation at tumor site." (PMID 31582772, 2019). "Notwithstanding some reports suggest a role for TLR3 in tumor progression." (PMID 29449840, 2018). "TLR-3 stimulation caused functional changes in TAMs, including increased phagocytic activity and upregulation of CD80 and CD86 expression with subsequent induction of CD4 T cell proliferation and tumor regression." (PMID 30420856, 2018). "Whether analysis of c-FLIP expression will improve the prediction of tumor sensitivity to TLR3 agonist alone is currently under investigation." (PMID 30158588, 2018). "Unfortunately, not much has been known about the role of TLR-3 in skewing tumor-associated M2 macrophages to tumor-protective M1 subtype." (PMID 30072995, 2018). "Therefore, the current study was designed to explore the importance of signaling through TLR-3 in reverting pro-tumorigenic M2 subtype to antitumorigenic M1 macrophages and subsequently studying its impact in controlling the tumor growth." (PMID 30072995, 2018). "Our study offers new insights into mycobacteria-activated c-Abl-BMP signaling abrogating TLR3 cascade, resulting in conditions that could plausibly fail to suppress tumor." (PMID 29449840, 2018). "Thes data suggest that TLR3 activation leads to increased activation of migratory DCs, which may lead to increased tumor antigen presentation in the tumor draining lymph nodes." (PMID 29755681, 2018). "PolyI:C-activated TLR3-TICAM-1 signaling also suppresses tumor growth via immune activation." (PMID 29041928, 2017). "The HCT116 cells generated tumors showed more scar tissues with some fine vascularization upon reovirus administration while the cells with TLR3 knockdown showed large areas of necrosis probably indicating a greater destruction of tumor tissues by necrosis thus making the tumors better contained." (PMID 28422714, 2017). "Hence, vaccine immunotherapy with TLR3 adjuvant enables to establish antitumor immunity against certain tumor types." (PMID 29312355, 2017). "TLR3 signaling suppresses tumor cell growth through down-regulation of c-Myc." (PMID 29041928, 2017). "The reported tumor-suppressive, anti-angiogenic, and apoptotic effects of TLR3 activation in the tumor microenvironment have predominantly been attributed to the induction of type I IFN and activation of effector cells that impair proliferation and induce apoptosis in tumor cells." (PMID 28717003, 2017). "Alternatively, TLR3 signaling may facilitate the infiltration of preexisting tumor-reactive CTLs into tumor sites by inducing chemokine production." (PMID 29312355, 2017). "Thus, TLR3 signaling functionally ameliorates the tumor microenvironment to potentiate antitumor immunity." (PMID 29312355, 2017). "IFN-α release in response to TLR3 stimulation proved essential for generation of type-1 polarized (IL-12 producing) DC which are essential for cross-priming, polarization and imprinting migratory properties of anti-tumor functional CD8+ T cells." (PMID 28445506, 2017).
tumor (continued). "However, TLR3/TICAM-1 signals convert these myeloid cells to tumoricidal effectors in tumor microenvironment." (PMID 29041928, 2017). "This study demonstrates an additional advantage of TLR3 adjuvant for direct therapeutic application to tumor cells: TLR3-targeted therapy may be of benefit to cancer patients by acting on both immune cells and tumor microenvironment." (PMID 29041928, 2017). "Nude mice were injected with tumor cells that were either unmodified or TLR3 silenced." (PMID 28422714, 2017). "Finally, immunostaining experiments in HNSCC samples showed that TLR3 was detected at higher levels in hypoxic tumors, with an enhancement of the staining in the periphery of the tumor, on the invasive front." (PMID 27791989, 2016). "Since TLR3 along with its downstream signaling responses have anti-cancer properties including immune-mediated tumor growth suppression and a direct apoptotic effect on TLR3 expressing cancer cells, TLR3 is currently being investigated for therapeutic interventions in cancer treatment." (PMID 27533082, 2016). "Thus, polyI:C treatment might not only target TLR3 in tumour cells and induce an anti-tumour type I interferon-rich environment or tumour apoptosis but will also target the maturation and antigen presentation of DCs specialised in the cross-presentation of tumour-associated antigens." (PMID 27911948, 2016). "At the translational level, low-grade inflammatory monocyte adaptation by TLR3 agonist may serve as a potential strategy to boost immune surveillance of tumor." (PMID 27891130, 2016). "Interestingly, several human tumours express high levels of TLR3 that is being targeted in immunotherapeutic protocols to initiate both innate and adaptive immune responses." (PMID 27911948, 2016). "TLR3 can detect self RNA upon cellular necrosis suggesting that the high expression of TLR3 within certain tumours might enable detection of RNA released from necrotic tumour cells." (PMID 27911948, 2016). "Furthermore, TLR3 activation by polyIC triggers the induction of cytokines, chemokines and other pro-inflammatory mediators, thus reinstating anti-tumor immunity." (PMID 27598772, 2016). "Overall, our results demonstrate that TLR3 stimulation induces the Warburg effect in HNC cells in vitro, and suggest that TLR3 may play a role in tumor adaptation to hypoxia." (PMID 27791989, 2016). "We demonstrate in vivo that EBERs can interact with TLR3 and induce tumor cells to produce cytokines in B16 synergetic tumor and human NPC xenograft models, in which macrophages are recruited and activated, leading to a favorable microenvironment for solid tumor growth." (PMID 26172457, 2015). "On the basis of our results that TLR3 activation hinders tumor growth but enriches breast CSCs, the examination of tumor size (or total number of cancer cells) instead of CSC sub-populations could lead to a different conclusion." (PMID 25257174, 2015). "Western blots confirmed the silence of TLR3 expression in tumor tissues." (PMID 26172457, 2015). "To examine in vivo whether EBERs trigger inflammatory response, we analyzed the tumor tissues from WT and TLR3−/− mice." (PMID 26172457, 2015). "Given that TLR3 has been well studied in innate anti-microbial responses against intracellular pathogens, it is possible that microbes within the tumor microenvironment may directly influence TLR3 responses." (PMID 26486085, 2015). "When TLR3 was knocked down with shRNA in C666–1, tumor growth was markedly inhibited (P < 0.05)." (PMID 26172457, 2015). "To further evaluate in vivo whether EBER-induced inflammation via TLR3 promotes tumor development, we subjected EBV-positive NPC C666–1 cells to tumor formation assay in nude mice." (PMID 26172457, 2015).